TTR (transthyretin)
Diseases named in the same sentence as TTR in open-access papers (continued):
Sharing a sentence is not in itself a finding about the gene and the disease.
familial amyloid polyneuropathy (continued). "More than 140 different mutations in the TTR gene have been reported, and the primary symptoms of ATTRv amyloidosis may vary depending on the genetic mutations involved." (PMID 37828588, 2023). "Although multiple aspects of the molecular pathophysiological mechanisms associated with ATTRv amyloidosis have been elucidated over the years, particularly related to the TTR protein, it is possible to hypothesize different pathogenetic pathways." (PMID 36552168, 2022). "Regarding molecular pathogenesis, ATTRv amyloidosis is a conformational disease caused by the aggregation of a specific protein, transthyretin (TTR), largely due to reduced folding stability and the consequent accumulation of insoluble amyloid fibrils through a dynamic process." (PMID 36552168, 2022). "In ATTRv amyloidosis and ATTRwt, a variant form of TTR was detected by the analyses." (PMID 35893595, 2022). "As these compounds prevent TTR aggregation in a gel-based assay in vitro, they might reduce the aggregation of unliganded TTR monomers in vivo, known to cause TTR amyloidosis and related comorbidities." (PMID 35334893, 2022). "Hereditary amyloidosis, or familial amyloid polyneuropathy, comprises a group of rare and fatal diseases frequently associated with disorders of the nervous system and heart, usually due to mutations in the gene encoding transthyretin (TTR)." (PMID 36156600, 2022). "In addition, TTR is also well known for its amyloidogenic propensity, causing several detrimental human diseases, such as senile systemic amyloidosis and familial amyloid polyneuropathy/cardiomyopathy." (PMID 34746240, 2021). "However, in the case of ATTRv amyloidosis, pathogenic TTR variants result in synthesis of unstable TTR tetramers, which then dissociate into monomers, misfold, and aggregate into amyloid fibrils." (PMID 34602081, 2021). "On the basis of genetic analysis of the TTR gene, these patients with ATTRv amyloidosis had 15 different TTR mutations: Val30Met, Val28Ser, Val28Met, Gly47Arg, Thr49Ser, Thr49Ile, Gly53Glu, Thr60Ala, Glu61Lys, Lys80Arg, Gly83Arg, Glu89Gln, Ala97Gly, Tyr114Ser, and Tyr114Cys." (PMID 31133063, 2019). "Such information may be clinically relevant: for instance, glycosylated forms of TTR have been observed only in individuals with the V30 M mutation associated with familial amyloid polyneuropathy (FAP), a hereditary disease often requiring liver transplantation." (PMID 40816420, 2025). "In contrast, the variant TTR protein that causes familial cardiac amyloidosis affects individuals in their fourth decade of life or later and causes familial amyloid cardiomyopathy, familial amyloid neuropathy, or mixed disease of cardiomyopathy and neuropathy." (PMID 40134993, 2025). "TTR amyloidosis causes several human diseases, such as senile systemic amyloidosis and familial amyloid cardiomyopathy/polyneuropathy; therefore, it is important to understand the molecular details of the structural deformation and aggregation mechanisms of TTR." (PMID 34746240, 2021). "In addition to liver transplantation to prevent the production of variant TTR, patisiran, a short interfering RNA, and inotersen, an antisense oligonucleotide, can reduce the production of TTR and have become available for ATTRv amyloidosis patients." (PMID 34361762, 2021). "For instance, familial amyloid polyneuropathy (FAP) is a hereditary disorder caused by mutations in the transthyretin (TTR) gene, leading to accumulations of misfolded TTR proteins and amyloid deposits in the peripheral nerves and other tissues." (PMID 39985020, 2025).
familial amyloid polyneuropathy (continued). "In the Phase 1 trial, a single intravenous dose of NTLA-2001 effectively knocked out the mutant TTR gene, reducing circulating TTR protein levels by up to 87% in patients with hereditary TTR amyloidosis with polyneuropathy." (PMID 41211267, 2025). "In 95% of cases, CA is caused by the deposition of misfolded monoclonal immunoglobulin light chains derived from an abnormal clone of plasma cell proliferation (AL amyloidosis) or misfolded transthyretin (TTR amyloidosis)." (PMID 40565972, 2025). "All seven TTR variants above were classified as pathogenic/likely pathogenic according to the ACMG criteria and consistent with a diagnosis of ATTRv amyloidosis (as detailed below)." (PMID 39878313, 2025). "Systemic administration is sufficient to target TTR in the liver and alleviate many of the devastating symptoms of TTR amyloidosis (ATTR), polyneuropathy, and cardiomyopathy." (PMID 40386915, 2025). "Contrary to initial beliefs that transthyretin-related familial amyloid polyneuropathy was endemic to certain areas, it is now known to occur worldwide." (PMID 40406766, 2025). "ATTR includes two main forms: ATTRv or transthyretin-related hereditary amyloidosis and ATTRwt or senile systemic amyloidosis (SSA)." (PMID 39451564, 2024). "Current treatments in ATTRv amyloidosis include disease-modifying drugs such as TTR stabilisers and TTR gene-silencing drugs, namely patisiran, vutrisiran and inotersen." (PMID 38622453, 2024). "They target the mRNA of the transthyretin gene and reduce the production of abnormal proteins that are responsible for ATTRv amyloidosis." (PMID 39286810, 2024). "The mutation presents 2 predominant phenotypes, such as primarily neurological involvement (TTR-FAP, familial amyloid polyneuropathy) or primarily cardiac involvement (TTR-FAC, familial amyloid cardiomyopathy)." (PMID 39451564, 2024). "The disease of transthyretin (TTR) amyloidosis (ATTR) has been known since the 1960s, and during the past 60 or so years, there has been a sustained period of steady discoveries that have led to the current model of ATTR pathogenesis." (PMID 39338387, 2024). "Tafamidis is the only FDA-approved treatment for TTR amyloidosis, a TTR stabilizer demonstrated in the ATTR-ACT trial to decrease mortality and cardiovascular hospitalizations." (PMID 39092395, 2024). "In contrast, cardiac tracer uptake on bone scintigraphy and troponin T levels increased in ATTRv amyloidosis patients treated with a TTR-stabilizer." (PMID 37843599, 2024). "Conversely, at present, three TTR gene silencers are approved for patients with ATTRv amyloidosis with neurological or mixed phenotype and stage 1 or 2 polyneuropathy." (PMID 38622453, 2024). "The primary objective of this study is to evaluate the utility of [99mTc]Tc-hydroxydiphosphonate (HDP) bone scintigraphy in analyzing treatment efficacy in ATTRv amyloidosis patients treated with patisiran and TTR-stabilizers." (PMID 37843599, 2024). "In a classic paper in 1978, it was shown that antibodies raised against amyloid fibrils isolated from patients with familial amyloid polyneuropathy (now known as ATTR-PN) cross-reacted with purified TTR protein." (PMID 39338387, 2024). "The only TTR stabiliser approved for ATTRv amyloidosis is tafamidis, with the indication for the treatment of patients with stage 1 polyneuropathy at the dose of 20 mg." (PMID 38622453, 2024). "Transthyretin (TTR) aggregation and amyloid formation are associated with several ATTR diseases, such as senile systemic amyloidosis (SSA) and familial amyloid polyneuropathy (FAP)." (PMID 36835140, 2023). "Transthyretin amyloidosis of wild type TTR can cause cardiomyopathy (ATTR-CM) in elderly patients and hereditary forms of TTR amyloidosis such as familial amyloid polyneuropathy (FAP) at younger ages." (PMID 36998202, 2023).
familial amyloid polyneuropathy (continued). "Hereditary transthyretin (ATTRv) amyloidosis with polyneuropathy, also known as familial amyloid polyneuropathy (FAP), represents a progressive, heterogeneous, severe, and multisystemic disease caused by pathogenic variants in the TTR gene." (PMID 37830598, 2023). "Among the modifying factors, the gender of the parent transmitting the mutation (i.e. the parent-of-origin effect) has been shown to have a significant effect on survival curve estimation on transthyretin familial amyloid polyneuropathy (ATTRv) families." (PMID 37561731, 2023). "As ATTRv amyloidosis is characterized by the deposition of transthyretin amyloid fibrils in organs and tissues, tissue biopsy using Congo red staining is commonly used for diagnosis, in conjunction with amyloid typing and genotyping." (PMID 37828588, 2023). "This agent was recently demonstrated to decrease serum TTR protein concentrations (> 95% reduction) through targeted knockout of TTR with a dose-dependent effect in six patients with ATTRv amyloidosis with polyneuropathy." (PMID 35929637, 2023). "In our center, 60 unrelated families with ATTRv amyloidosis have been identified by sequencing the TTR gene." (PMID 36311011, 2022). "First, we analyzed TTR aggregates by immunoblotting analysis of the EVs of patients with ATTRv amyloidosis and healthy individuals (N = 6)." (PMID 35402512, 2022). "Negligible TTR concentrations were seen in the urine of the asymptomatic carriers of ATTRv amyloidosis." (PMID 35893595, 2022). "Overall, TTR tetramer concentration in healthy donors carrying wild-type TTR gene (5.25 μM) was higher than that in E61K ATTRv amyloidosis patients (3.63 μM)." (PMID 36311011, 2022). "In our study, why were urinary TTR concentrations correlated with the progression of ATTRv amyloidosis?" (PMID 35893595, 2022). "Compared to healthy subjects, patients with ATTRv amyloidosis showed decreased TTR aggregates and increased EV markers." (PMID 35402512, 2022). "A detailed analysis of TTR aggregation in the EV pathway will help further elucidate the pathogenesis of ATTRv amyloidosis." (PMID 35402512, 2022). "The aim of the study was to evaluate the utility of urinary TTR in the diagnosis of ATTRv amyloidosis." (PMID 35893595, 2022). "The symptoms of this disease are comparable to an autonomic dominant NDD, familial amyloid polyneuropathy (FAP), which results from mutations in the transthyretin (TTR) gene." (PMID 36515657, 2022). "The different forms of senile or familial systemic TTR amyloidosis (A-TTR) are characterized by the presence, in the affected tissues/organs, of extracellular deposits of amyloid fibrils composed of TTR polymers." (PMID 35337074, 2022). "These aspects are of great importance to assess the possible use of this plant polyphenols as natural TTR stabilizers to prevent the onset of different sporadic and familial TTR amyloidosis." (PMID 35337074, 2022). "In this study, five ATTRv amyloidosis families carrying TTR E61Kmutation and their clinical symptoms were reported." (PMID 36311011, 2022). "Backgrounds: Transthyretin familial amyloid polyneuropathy (TTR-FAP) is frequently misdiagnosed as chronic inflammatory demyelinating polyneuropathy (CIDP) because of similar phenotypes in the two diseases." (PMID 33716932, 2021). "Transthyretin familial amyloid neuropathy (TTR-FAP) is a multiple systemic disorder caused by TTR gene mutation and characterized by extracellular deposition of transthyretin-derived amyloid fibrils in peripheral and autonomic nerves and other organs." (PMID 33716932, 2021). "Using the CRISPR gene editing technique, first steps are being made in that direction for ATTRv amyloidosis now, however, they have been, again, limited to hepatic TTR production so far." (PMID 34719408, 2021).
familial amyloid polyneuropathy (continued). "There are also other forms of IPN such as transthyretin familial amyloid polyneuropathy (TTR-FAP), a severe hereditary neuropathy affecting the sensorimotor and autonomic function as well as other organs caused by mutation of the TTR gene." (PMID 34306035, 2021). "TTR instability is also a key feature in familial amyloid polyneuropathy (FAP), a systemic amyloidosis that is usually caused by mutations in TTR." (PMID 34429155, 2021). "Technetium Pyrophosphate Scintigraphy (PYP scan) is a nuclear imaging study which detects cardiac transthyretin and can be used (in conjunction with other clinical investigations) to diagnose TTR amyloidosis." (PMID 33595871, 2021). "Liver-transplanted ATTRv amyloidosis patients present continued progression of CNS and eye symptoms if the choroid plexus and retina continue to produce mutant TTR." (PMID 34719408, 2021). "From liver-transplanted ATTRv amyloidosis patients, we have learned that CNS and eye symptoms cannot be stopped if the choroid plexus and retina continue to produce mutant TTR." (PMID 34719408, 2021). "Observations of nerve biopsy specimens from patients with ATTRv amyloidosis have suggested that globular structures of similar diameter to Aβ intermediates were generated from amorphous electron-dense materials containing TTR." (PMID 34443678, 2021). "In 2018, FDA approved the first RNA interference drug, Patisiran, which selectively silences transthyretin (TTR) expression and has been applied to familial amyloid polyneuropathy (FAP) treatment." (PMID 34772918, 2021). "Diflunisal is a nonsteroidal anti-inflammatory drug indicated for stage I and II of transthyretin familial amyloid polyneuropathy (TTR-FAP) according to the European consensus for diagnosis, management, and treatment of this disease." (PMID 34349654, 2021). "In familial amyloid polyneuropathies (FAP), which are associated with peripheral neuropathy, mutations in the genes encoding TTR, gelsolin, or apolipoprotein A1 cause amyloid formation." (PMID 32604774, 2020). "Transthyretin familial amyloid polyneuropathy (ATTR-FAP) is a rare autosomal dominant inherited disease affecting multiple organ systems." (PMID 33054844, 2020). "Transthyretin familial amyloid polyneuropathy (ATTR-FAP) is an autosomal dominant inherited condition with over 100 different mutations identified worldwide in the transthyretin (TTR) gene." (PMID 33054844, 2020). "In recent years, it has been shown that tolcapone is a potent inhibitor of the amyloid aggregation process of the transthyretin protein, and acts by stabilizing the structure of the protein, reducing the progression of familial amyloid polyneuropathy." (PMID 32708961, 2020). "TTR aggregates and ER stress are present in dorsal root ganglia of TTR transgenic mice, suggesting a role in familial amyloid polyneuropathy." (PMID 32604774, 2020). "Protein TTR misfolding and tissue deposition of amyloid start before the appearance of symptoms in ATTRv amyloidosis." (PMID 33316911, 2020). "Deposits of misfolded transthyretin (TTR) protein around sensory and autonomic nerves, characterize familial amyloid polyneuropathy with NeuP being an early symptom." (PMID 31751545, 2019). "To facilitate diagnosis, we analyzed data patterns of patients with transthyretin familial amyloid polyneuropathy (TTR‐FAP) and compared them to polyneuropathies of different etiology for clinical and electrophysiological discriminators." (PMID 29568686, 2018). "Additional in vivo studies are required to determine how the C-terminal TTR fragment is involved in the pathogenesis of TTR amyloidosis." (PMID 30552363, 2018). "Transthyretin (TTR)-related familial amyloid polyneuropathy (TTR-FAP) is a life-threatening autosomal dominant, systemic disease." (PMID 30286783, 2018).
familial amyloid polyneuropathy (continued). "Recently, RLS was found to be more prevalent in familial amyloid polyneuropathy related to transthyretin as compared to controls proposing that peripheral pathway play a part in RLS pathogenesis." (PMID 28212408, 2017). "The relationship between familial amyloid polyneuropathy (FAP), which is caused by mutated transthyretin (TTR), and inflammation has only recently been noted." (PMID 28484271, 2017). "Familial amyloid polyneuropathy (FAP) is a rare neurodegenerative disease showing autosomal dominant inheritance, which is caused by deposition of mutated transthyretin (TTR)-derived amyloid fibrils in several organs." (PMID 28484271, 2017). "To confirm these results in another mouse disease model, we evaluated Toc-HDO in the V30M Transthyretin (TTR) transgenic mouse, which is the model of familial amyloid polyneuropathy." (PMID 26258894, 2015). "Transthyretin (TTR), a human serum protein expressed by the liver, is the cause of familial amyloid polyneuropathy (FAP)." (PMID 26437390, 2015). "Mutations of the gene encoding transthyretin (TTR), expressed in vast amounts by the liver, result in a complex degenerative disease, termed familial amyloid polyneuropathy (FAP)." (PMID 26437390, 2015). "Transthyretin is associated with several pathologies such as senile systemic amyloidosis (SSA), familial amyloid polyneuropathy (FAP) and familial amyloid cardiomyopathy (FAC) which are characterized by extracellular deposition of insoluble amyloid fibrils." (PMID 26545113, 2015). "Wild type transthyretin (TTR) is responsible for senile systemic amyloidosis, and more than 100 mutations in the TTR gene are involved in familial amyloid polyneuropathy." (PMID 25086037, 2014). "TTR amyloidosis can present as a progressive, axonal sensory autonomic and motor neuropathy (familial amyloidotic polyneuropathy; TTR-FAP, also known as FAP or ATTR-PN) or as an infiltrative cardiomyopathy (familial amyloid cardiomyopathy)." (PMID 23425518, 2013). "Tafamidis, a transthyretin (TTR) kinetic stabilizer, delayed neuropathic progression in patients with Val30Met TTR familial amyloid polyneuropathy (TTR-FAP) in an 18-month randomized controlled trial (study Fx-005)." (PMID 23974642, 2013). "Furtherdevelopment of B26 could lead to a second generation of inhibitorsof TTR amyloidogenesis that may widen the current options for preventionand cure of TTR amyloidosis." (PMID 40421796, 2025). "In addition to these tetramer stabilizers, TTR silencer drugs, including patisiran, vutrisiran, inotersen, and eplontersen, which reduce the hepatic synthesis of TTR, have also been used in patients with ATTRv amyloidosis." (PMID 40429804, 2025). "However, TTR amyloidosis also affects the eye, suggesting a need for reducing ocular TTR gene expression." (PMID 40386915, 2025). "Transthyretin (TTR) is a 56 kDa tetrameric protein complexthattransports thyroxine and retinol but can misfold, causing amyloiddiseases, such as senile systemic amyloidosis, familial amyloid cardiomyopathy,and familial amyloid polyneuropathy." (PMID 41220233, 2025). "Other uncommon illnesses may also mimic FD, such as Whipple’s illness, transthyretin-related familial amyloid polyneuropathy, or mitochondrial disorders." (PMID 40218952, 2025). "For example, tetracyclines and some polyphenols are able to interfere with aggregation of several amyloidogenic proteins, such as amyloid polypeptide (type-2 diabetes) and transthyretin (senile systemic amyloidosis, familial amyloid polyneuropathy, and cardiomyopathy)." (PMID 38732194, 2024). "It is not surprising that cardiac involvement and familial amyloid polyneuropathy are more common in individuals with TTR gene mutations, which are endemic in Europe and Asia." (PMID 38111336, 2024).